CAV1 (caveolin 1)
Diseases named in the same sentence as CAV1 in open-access papers (continued):
Sharing a sentence is not in itself a finding about the gene and the disease.
cancer (continued). "Caveolin-1 (CAV1), the major constituent of caveolae, plays a pivotal role in various cellular biological functions, including cancer and inflammation." (PMID 28593998, 2017). "In cancer cells, BKCa can band with Cav3.2, caveolin-1, IP3R3 and FAK to regulate cancer biological behaviors." (PMID 27233075, 2016). "Three proteins, CAV1, CAV2, and RAGE, were higher in all control tissues as compared to corresponding cancer tissues." (PMID 26930711, 2016). "However, whether Cav-1 participates cancer cell polarity is not well known." (PMID 26919102, 2016). "However, despite knowledge of its expression pattern and roles in different cancers, it is still unclear whether CAV1 expression is a property that accompanies or directly drives altered metabolism, or if changes in energy balance modulate CAV1 level towards or against cancer progression." (PMID 27852311, 2016). "Caveolin-1 (CAV1) is the principal structural protein of caveolae and closely correlates with multidrug resistance in cancer cells." (PMID 26843476, 2016). "The CAV1 gene consists of three exons and maps to 7q31.1, where is close to a known fragile site (FRA7G) frequently deleted in cancer." (PMID 26431273, 2015). "We recently demonstrated that the CAV1 gene was down-regulated, when poorly differentiated thyroid FTC-133 cancer cells formed spheroids under simulated microgravity conditions." (PMID 26633361, 2015). "It should be mentioned that of Cav-1 is mostly overexpressed during neoplastic progression, and that its role in cancer biology appears to be multidimensional, as it may promote tumorigenesis and metastasis, especially in most advanced cancers, while behaving as an anti-oncogene in other contexts." (PMID 25374561, 2014). "The human caveolin-1 locus revealed that it maps to 7q31.1, adjacent to the marker D7S522, a fragile site with deletions in many tumors in cancers such as breast, prostate, and ovarian." (PMID 25594072, 2014). "Thus, an increase of caveolin-1 might serve for enhanced mitochondrial stability under stressful conditions like liver fibrosis and inflammation as well as for an additional survival strategy for cancer cells." (PMID 23339737, 2013). "For example, Cav-1 has been shown to facilitate both ERK and AKT signalling in cancer cells derived from colon, prostate, epidermis and smooth muscle, and is associated with promoting cell invasion, proliferation, angiogenesis and multi-drug resistance." (PMID 24119769, 2013). "Previously, we found that CTSB is localized to caveolar membrane microdomains in cancer cell lines including IBC, and therefore, we also examined the expression of caveolin-1 (cav-1), a structural protein of caveolae in IBC versus non-IBC tissues." (PMID 21199580, 2011). "However, current research has limitations, and future studies should focus on the following areas: Besides macroautophagy, further investigation into the crosstalk between Cav-1 and mitophagy or CMA is needed especially in cancer and metabolic diseases." (PMID 41030451, 2025). "Moreover, CAV1 coimmunoprecipitated with EGFR in JHOS2 cells, indicative of a direct interaction between these proteins, as previously observed in other cancers 36,38." (PMID 39482470, 2025). "Additionally, Cav1 inhibits the Ras-MAPK/ERK pathway and PI3K/AKT pathways, both frequently activated in cancer cells to promote survival and proliferation." (PMID 40963741, 2025). "Such in-depth differentiated modulation of CAV1 will allow protection of the skin without substantially changing the radiosensitivity of deeper-lying cancer cells." (PMID 41516288, 2025). "In addition, high expression of CAV1 predicted worse prognosis in OSCC, can inhibit ferroptosis and cisplatin sensitivity in cancer cells, promoting migration and invasion, and can affect the immune cell infiltration." (PMID 39941896, 2025).
cancer (continued). "By contrast, the overexpressed miR-6126 mimics suppressed their target, GRP78 mRNA, in both P2- and P2S-treated A549 cancer cells, suggesting that miR-6126-mediated mRNA suppression does not depend on Ago2/CAV1 interaction." (PMID 38649663, 2024). "Among these inhibitors, TM attenuated Ago2/CAV1 interaction in both A549 and HCC1806 cancer cells." (PMID 38649663, 2024). "Blockage of Ago2/CAV1 interaction by the AID system has the same effects as P2 peptides on miRNA regulation and cancer cell behavior, suggesting that the altered miRNA regulation and cancer cell behavior by P2 peptides indeed result from the disruption of Ago2/CAV1 interaction." (PMID 38649663, 2024). "Blocking Ago2/CAV1 interaction in cancer cells with P2 peptides decreased the numbers of tumorsphere-forming cells in the A549 cancer cell populations and HCC1806 cancer cell populations (Fig. 4Dii)." (PMID 38649663, 2024). "Because Ago2/CAV1 interaction is required, as a secondary event, in miRNA-mediated mRNA suppression (e.g., miR-3613-3p-mediated suppression of SCAI), this interaction increases the complexity of miRNA actions in cancer (blue arrows in right panel)." (PMID 38649663, 2024). "Importantly, the intricate interplay between CAV1, the TME, and cancer metabolism underscores the complexity of cancer biology and opens avenues for novel therapeutic strategies targeting metabolic dependencies in cancer." (PMID 39596307, 2024). "However, other studies obtained contradictory results, finding MT1-MMP in caveolin-1-positive membrane domains and vesicles and observing partial inhibition of MT1-MMP internalization when caveolae were disrupted in cancer cells." (PMID 36982142, 2023). "The deletion of CAV1, a membrane-intrinsic protein with inhibitory effects on LUAD, in TME may affect the survival of cancer cells." (PMID 36881404, 2023). "We have used a quantitative, unbiased and semi-automated method to measure in situ protein expression of clathrin and caveolin-1 in cancerous and paired normal (cancer adjacent, non-cancerous) human prostate tissue." (PMID 36869937, 2023). "Given its dual roles in cancer that impart both anti- and pro-apoptotic functions to caveolin-1, this protein was excluded as a putative target for counteracting vemurafenib resistance from further in vitro validation studies." (PMID 37629086, 2023). "In our study, by using exosome inhibitors, we found that Cav-1 expression levels were reduced in cancer cell cultures without exosomes, which indicated that exosomes can be used as vectors to transport Cav-1." (PMID 37056561, 2023). "While CAV1 is reported to have a role in endocytosis, the importance of CAV1-mediated endocytosis in cancer survival has not been elucidated." (PMID 37919422, 2023). "In another study, it was found that CAFs can induce cancer stemness and gemcitabine resistance through leukemia inhibitory factor (LIF), which is promoted by circFARP1 specifically expressed in CAFs via direct binding to caveolin 1 (CAV1)." (PMID 37819576, 2023). "In addition, gene network analysis regarding to mass-type ER-positive cancers showed that ESR1, BIRC5, CAV1, FGFR1, IL6, MIR27, and PTTG1 were upregulated." (PMID 37391754, 2023). "A possible role of the PHB1/ANX2/CD36/CAV1 interactome in cancer progression remains to be determined and put into the context of what is known about other proteins, such as FATP1, which also regulate FA transport in cancer cells." (PMID 35991116, 2022). "On the other hand, none of the dHCPPIs was the same for all cancer types studied, and five interactions were the same in at most seven different cancers (i.e., CAV1-CTNNB1, COL1A1-IGFBP3, LDHA-LDHB, PCNA-GAPDH, and PSMB7-PSMB3)." (PMID 36422095, 2022). "Our laboratory has recently demonstrated that CAV1 increases migration, invasion, and metastasis of cancer cells lacking E-cadherin in a manner dependent on Y14 phosphorylation and activation of a Rab5/Rac1 signaling axis." (PMID 35740528, 2022).
cancer (continued). "Further, CAV1 expression was found to directly correlate with nanoparticle albumin conjugate (nab) of paclitaxel sensitivity in pancreas-cancer and NSCLC cells and pancreas-cancer mouse xenograft models." (PMID 35158857, 2022). "We did not have any data related to family history of cancer; however, the expression of CAV-1 can be effected by this cofounding marker." (PMID 35641515, 2022). "Interestingly, caveolin-1, GRP78, D2R, TLR7, and Src signaling pathways are important not only during cancer formation but also during JEV-mediated neurodegeneration." (PMID 36560690, 2022). "It was observed that fibroblasts surrounding malignant cells have a low Cav-1 expression, high MCT4 expression and enhanced aerobic glycolysis, which mirrors the simultaneous increase of mitochondrial activity in the adjacent epithelial cancer cells." (PMID 35565415, 2022). "In an in vitro co-culture model, ROS derived from cancer cells (MCF-7 cells) induced autophagy in fibroblasts and consequently reduced the expression of Caveolin-1 (Cav-1), which led to the development of myofibroblast characteristics (i.e., upregulation of α-SMA, calponin, and vimentin)." (PMID 33498875, 2021). "The negatively correlated genes were enriched in “calcium signaling pathway,” “PPAR signaling pathway,” and “proteoglycans in cancer”, and ACACB, PPARG, CAV1 may be the core of these genes." (PMID 34257557, 2021). "Taken together, these results suggest that CAV-1, Smad7, saa3, and miRNAs might be candidates to target the CAF-mediated NF-κB signaling pathway in cancers." (PMID 34108441, 2021). "This study also revealed that siRNA-mediated silencing of caveolin-1 increased H-1PV transduction of cancer cells, suggesting that caveolin-1 is a negative modulator of the H-1PV life cycle." (PMID 34452286, 2021). "Then, we tested whether double knockdown of CAV-1 and LOX-1 enhanced the anti-cancer activity of celastrol in 786-O cells." (PMID 33935779, 2021). "In addition, the insulin receptor (IR) can be activated by phosphorylated Cav-1 and binds to LDL receptor–related protein 6, thereby mediating the Akt-mTORC1 signaling pathway and regulating aerobic glycolysis in cancer cells." (PMID 34955837, 2021). "Here we found that RV-loaded GSH-NSs can target cancer cells regardless of their caveolin-1 expression." (PMID 33564618, 2021). "Cav1 was reported to block EGF-mediated proliferation, migration and invasion by targeting downstream effectors (mainly MEK/ERK and Pi3K/AKT/mTor) in various cancers." (PMID 34207120, 2021). "AT1R probably took part in the CAV1 and FOXM1 signaling pathway in those cancer cells." (PMID 33673178, 2021). "Importantly, our model provides a connection between cancer metabolic commitments and immune evasion and provides clearly defined targets for drug development (ODC, CAV1-mediated endocytosis, ATP13A3)." (PMID 34945011, 2021). "Further, CAV1 stimulates Rho- and force-dependent contraction, matrix alignment, and TME stiffening through regulation of p190RhoGAP favouring directional migration and invasiveness of carcinoma cells in vitro." (PMID 33739025, 2021). "Moreover, CAV1 protein level in the stroma, ATG4C protein level in cancer cells, and high expression of both CAV1 and ATG4C protein in the stroma are correlated with histologic subtypes of EOC patients." (PMID 32401768, 2020). "Cav‐1 can be downregulated by the aberrant promoter methylation of CAV1 in the stage and may be crucial in the development of many cancers." (PMID 32508059, 2020). "In the present study, over-expressed lnc-BMP1-1 could increase the expression of Cav-1 and enhance the sensitivity of A549 cells to Doxorubicin, a conclusion that sheds light on the usage of lnc-BMP1-1 in cancer treatment." (PMID 31901898, 2020). "In addition, C7 was an enrichment cluster of squamous morphology cancer cell lines, mostly made of HNSC and ESCA and was characterized by high level of CDH1, CLDN7 and CAV1." (PMID 32874774, 2020).
cancer (continued). "In cancer cells, CAV1 has both positive and negative impacts on cancer development—relating to cell invasion and metastasis as well as cancer repression." (PMID 32401768, 2020). "In this cluster, Rac Family Small GTPase 1 (RAC1), Caveolin 1 (CAV1), Low-density lipoprotein receptor-related protein 6 (LRP6) and collagen type I alpha 1 chain (COL1A1) were identified as proteins shown to promote EMT in various cancer." (PMID 33050615, 2020). "Wnt/β-catenin signaling and expression patterns of important genes in cancer cell growth and survival, which were further suggested to play a role in three-dimensional aggregation, such as NFKB2, VEGFA, CTGF, CAV1, BCL2(L1), or SNAI1, were clearly affected by DEX." (PMID 32033410, 2020). "Moreover, both CAV1 and ATG4C are active participators in the process of cancer cell migration and invasion." (PMID 32401768, 2020). "Taken together, CAV1 and ATG4C may act as the targets or signaling molecules in cancer progression and contribute to cancer invasion and metastasis." (PMID 32401768, 2020). "CD44 plays not only a role in EMT but also is a dedifferentiation marker that has been formerly reported to be highly expressed in anaplastic lesions and is correlated with cancer stem cells in PDAC and Caveolin 1 which was formerly suggested to be considered as an aggressiveness marker in PDAC." (PMID 32228510, 2020). "A positive colocalization signal was observed for the MDA-7/IL-24-CHC antibody pairs, but not for the MDA-7/IL-24-caveolin-1 antibody pair, thereby indicating a specific association of internalizing MDA-7/IL-24 with CHC in nonfractionated cancer cells." (PMID 31489119, 2019). "Caveolin-1 (CAV1) is a known a biomarker of the catabolic CAF phenotype, which is reversible upon treatment with antioxidants and is a strong predictor of a poor clinical outcome in various types of human cancers." (PMID 31014370, 2019). "There is evidence from our results that an increase in CAV-1 expression can differentiate non-metastatic cancer from normal, but this requires a more extensive study." (PMID 31889941, 2019). "Herein, we expressed phosphomimetic Y14D, wild type, and non-phosphorylatable Y14F forms of Cav1 in MDA-MB-435 cancer cells." (PMID 31803361, 2019). "Although elevated Cav1 expression has been observed in several MDR cancer cells, high level of Cav1 does not confer MDR14–16." (PMID 31113938, 2019). "In keeping with deposition of PAD4 through vesicle release, EVs isolated from cancer cell conditioned media contained PAD4 as well as many characteristic EV markers including caveolin-1 and β-catenin and lacked markers of ER and of Golgi apparatus." (PMID 30429478, 2018). "For this, CAV1 and ITGB1 were analysed in a cohort of 435 patients (TMA_1) in a tissue microarray (TMA) format, including one core from a benign area and three cores from cancer areas in each patient." (PMID 29402961, 2018). "Considering such roles of phosphorylated caveolin-1, it is not surprising that cancer cell migration is enhanced by inhibiting neddylation." (PMID 29301501, 2018). "To address cell-surface HER2 stability in CAV1-positive vs. CAV1 negative cells, we first explored protein–protein associations between HER2 and CAV1 in a panel of cancer cell lines." (PMID 30510281, 2018). "When CAV1 is coupled with an oncogene, CAV1 knockout mice appear more prone to progress to aggressive forms of cancers than in mice without the CAV1 knockout." (PMID 30042829, 2018). "In conclusion, our study establishes the inverse relationship between CAV1 expression and HER2 localization at the cell membrane, and how this relationship can be pharmacologically modulated to augment HER2-targeted therapy of various cancers." (PMID 30510281, 2018). "Cav-1 expression levels (Cav-1/GAPDH) were detected in a range of 0.66–1.89 (mean 1.27), 0.07–3.43 (mean 1.09), and 0.00–3.40 (mean 1.41) in normal tissues, primary tumors, and cancer cell lines, respectively." (PMID 29141593, 2017).
cancer (continued). "Understanding the downstream molecule responsible for Cav-1-mediated electrotaxis is important in the development of novel strategies to fight cancer invasion and metastasis." (PMID 29221162, 2017). "Taken together, these results demonstrated that MIM-B and caveolin-1 expression levels were higher in cancer tissues than in paired adjacent normal tissues and that MIM-B and caveolin-1 expression levels were correlated with HCC clinico-pathologic characteristics." (PMID 29221140, 2017). "In the multivariate analysis, tumoral Cav-1 protein in metastatic lymph node showed prognostic significance for relapse-free survival (RFS, HR, 3.934; 95% CI, 1.882–8.224; P = 0.001) and cancer-specific survival outcome (CSS, HR, 2.681; 95% CI, 1.613–8.623; P = 0.002)." (PMID 28828003, 2017). "Notably, MMP14 is ‐ together with AXL, caveolin 1 (CAV1) and ITGA5 ‐ among the top genes contributing to the differentiation of cancer from normal tissue." (PMID 28596300, 2017). "Compared to adjacent noncancerous tissues, 46 and 30 cancers tissues showed down-and up-regulation of Cav-1 mRNA, respectively." (PMID 29141593, 2017). "At the highest dilution of cancer cells of 1:50,000 spiked SKBR3 cells, which is more biologically relevant, expression of all 11 DTC biomarker genes were still detected in filtered BM samples, but only 1 gene (CAV1) was detectable in the unfiltered samples." (PMID 28129357, 2017). "Although P-glycoprotein is reportedly located in lipid rafts and associated with CAV111, 12, the influence of the interaction between CAV1 and P-glycoprotein on the development and progression of MDR in cancer cells is largely unknown." (PMID 26843476, 2016). "The upregulation of Cav-1 and MT1-MMP expression would facilitate cancer cell migration." (PMID 26919102, 2016). "Interestingly, we highlighted evidences that CAV1 interacts with known mediators of altered metabolism, e.g. LDHA, PKM2 and FASN, which are currently being studied as cancer drug targets." (PMID 27852311, 2016). "Although the negative role of Cav-1 in cancer is well documented, its role in brain injury and BBB dysfunction remains controversial." (PMID 27708218, 2016). "However, CAV1 (p = 8.3 × 10−6) and CD36 (p = 0.01) were both significantly amplified across all cancers according to the genome-wide GISTIC analysis." (PMID 26725848, 2016). "However, since Cav-1 expression was usually focal in human primary PCa and ACC1 immunostaining levels varied among cancer cells, we compared the ACC1 levels in the Cav-1+ and Cav-1- areas in the Cav-1+ PCa specimens." (PMID 27331874, 2016). "Tyrosine phosphorylated Cav1 (pCav1) functions in concert with Galectin-3 (Gal3) and the galectin lattice to stabilize focal adhesion kinase (FAK) within focal adhesions (FAs) and promote cancer cell motility." (PMID 25942420, 2015). "The expression of caveolin-1 could mediate endocytosis and promote the internalization of T-DM1 into HER-2 positive cancer cells." (PMID 26172389, 2015). "In the area of lower differentiation status where cancer cells are crowded by the active proliferation and have increased nuclear/cytoplasmic ratio without keratinization, we clearly observed a Brm+, CD44+, MET+, and CAV1+ phenotype in almost all cases." (PMID 25673149, 2015). "Our data support a role for PTRF/cavin-1, through caveolae formation, as an attenuator of the non-caveolar functionality of Cav1 in Gal3-Cav1 signalling and regulation of focal adhesion dynamics and cancer cell migration." (PMID 25942420, 2015). "For example, HAX1, RNF2, and CAV1 interact with ABCB1, and these proteins are also prioritized in the top 5 candidate list in VCR study using ProteinRank and involved in chemoresistance in various carcinoma cells." (PMID 26039373, 2015).